U3 (Small nucleolar RNA U3 )
Synonyms: LOC124904668
Gene: Small nucleolar RNA gene on chromosome 1 (219,962,652 to 219,962,865, forward strand). Ensembl gene ENSG00000221673.
Gene Ontology:
Biological process: RNA processing
Cellular component: nucleolus
Homologues: Orthologues: macaque U3 (78% identical). Paralogues in human: SNORD3P1 (69% identical), U3 (69% identical), U3 (66% identical), U3 (65% identical), U3 (64% identical), SNORD3E (64% identical), SNORD3H (64% identical), U3 (63% identical), SNORD3G (62% identical), U3 (62% identical), U3 (61% identical), SNORD3D (61% identical), and 12 more.